STAT6 (signal transducer and activator of transcription 6)
Diseases named in the same sentence as STAT6 in open-access papers (continued):
Sharing a sentence is not in itself a finding about the gene and the disease.
lung carcinoma (continued). "Furthermore, data from the UCSC Cancer Genomics Browser1 indicate that STAT6 is highly expressed in many types of carcinoma including thyroid, breast, and lung cancer." (PMID 31798581, 2019). "The different expression levels of STAT6 in carcinoma and para-carcinoma tissues suggest that STAT6 might play an important role in lung cancer." (PMID 31798581, 2019). "We detected high expression of STAT6 in CD11b+ cells of lung carcinoma." (PMID 31798581, 2019). "In addition, activated STAT6 regulated the signaling pathway to promote the process of lung cancer and might be a therapeutic target for lung cancer." (PMID 36968603, 2023). "STAT6 may be a new therapeutic target for the prevention and treatment of lung cancer." (PMID 31798581, 2019). "Immunohistochemistry analyzed the cellular localization of p-STAT6, p-JAK2, and ALK in EML4-ALK-positive lung cancer tissues." (PMID 34090412, 2021). "It has also been reported that STAT6 is a survival factor in human prostate and unphosphorylated STAT6 increases the expression of COX-2, thereby protecting nonsmall cell lung cancer (NSCLC) against apoptosis." (PMID 24191252, 2013). "This suggests that FA may hinder lung cancer cells from growing and spreading by blocking the JAK2/STAT6 immune signaling pathway." (PMID 40487371, 2025). "Our findings suggest that STAT6 has the potential as a biomarker in patients with NSCLC, which may contribute to the development of novel preventive and treatment approaches for lung cancer." (PMID 31798581, 2019). "This implies that the effects of STAT6 silencing are general and not restricted to any particular lung cancer cell line." (PMID 22162773, 2011). "The exact role of STAT6 in lung cancer carcinogenesis and progression has not been verified." (PMID 31798581, 2019).
mesenchymal tumor (21 papers, 2021 to 2026). "PURPOSE: Solitary fibrous tumour (SFT) is a rare mesenchymal neoplasm molecularly defined by the NAB2::STAT6 gene fusion (GF), an aberrant transcriptional regulator whose functions beyond EGR1 activation remain incompletely understood." (PMID 41665771, 2026). "The amplification of DDIT3 and STAT6 may vary depending on the amplicon length in cases of mesenchymal neoplasms with 12q13-15 amplification." (PMID 38275873, 2024). "Diffuse and intense STAT6 nuclear staining may accurately distinguish breast SFT from other types of mesenchymal tumor; however, the utilization of STAT6 immunostain for the preoperative diagnosis of breast SFT has been reported in only 4 cases." (PMID 36550858, 2022). "Solitary fibrous tumour (SFT) is a rare and ubiquitous fibroblastic mesenchymal neoplasm with a specific histological architecture, which harbours an intrachromosomal NAB2/STAT6 fusion gene and shows nuclear immunoreactivity for STAT6." (PMID 36077723, 2022).
prostate carcinoma (20 papers, 2010 to 2024). A carcinoma that arises from epithelial cells of the prostate gland. "The KM survival shows that the patients with prostate cancer held STAT6 and SOX2 alterations, linked to the decreased survival of the patients." (PMID 35719950, 2022). "The point mutations and their types in SOX2 and STAT6 in prostate cancer patients shows significant mutation frequency." (PMID 35719950, 2022). "STAT6 has been recently linked to HPN as one of the most robust pair of biomarkers for prostate cancer using an integrative approach that linked several microarray datasets." (PMID 20805891, 2010). "Several miRNAs have been identified that act as tumor suppressors in prostate cancer by targeting STAT6, and inhibit the growth and metastasis of tumor cells, and induce apoptosis." (PMID 35269804, 2022). "Weighted gene co-expression network analysis (WGCNA) suggests a set of five dysregulated hub genes (MAF, STAT6, SOX2, FOXO1, and WNT3A) that played crucial roles in biological pathways associated with prostate cancer progression." (PMID 35719950, 2022). "Highly expressed STAT6 is an important survival factor for prostate cancer cells and controls the disease progression." (PMID 34090412, 2021). "Down-regulation of STAT6 in a prostate cancer cell line results in reduced cell viability, induced apoptosis and impaired migration." (PMID 27533463, 2016). "It has been reported that AnxA2 associates with signal transducer and activator of transcription 6 (STAT6) and stimulates STAT6 transcriptional activity in prostate cancer cells." (PMID 25222280, 2014). "In prostate cancer cells, AnxA2 physically interacts with STAT6 to stabilize cytosolic levels of phosphorylated STAT6 and promote its nuclear localization." (PMID 25222280, 2014). "STAT6 over-expression and activity have been previously reported to correlate with promotion of cell migration in prostate cancer cells and invasiveness growth in glioblastoma." (PMID 24167634, 2013). "Similarly, a previous study showed that Anxa2 binds to STAT6 and promotes its activity in prostate cancer cells." (PMID 26307676, 2015). "In addition, VEGF induces Tyr phosphorylation and nuclear translocation of Activator of Transcription 6 (STAT6), which interacts with AnxA2 in prostate cancer cells, suggesting that one of the angiogenic effects of VEGF is to regulate the expression of AnxA2 directly or indirectly." (PMID 23555942, 2013). "We found overexpressed STAT6 and SOX2 and proposed them as candidate biomarkers and potential targets in prostate cancer." (PMID 35719950, 2022). "Altogether, the results signify that STAT6 and SOX2 and their genomic alterations can be explored in therapeutic interventions of prostate cancer for precision oncology, utilizing early diagnosis and target-propelled therapy." (PMID 35719950, 2022). "We therefore propose that although the interleukin-4/STAT6 axis does not appear to be involved in therapy resistance, it does play a crucial role in the colony-forming abilities of the basal cell population in prostate cancer." (PMID 28553931, 2017).
eosinophilia (19 papers, 2011 to 2025). "IL-13-driven eosinophil infiltration of the esophagus induced eosinophilia and eotaxin-1 expression in a STAT6-dependent and MID-1-dependent manner." (PMID 38026128, 2023). "STAT6 regulates many pathological features of the pneumonia response in animal models, including airway eosinophilia, Th2 cell differentiation, and IgE production by B cells." (PMID 35204186, 2022). "The JAK/STAT6 pathway has been reported to regulate pathological characteristics in asthmatic animal models, such as Th2 cell differentiation, and airway eosinophilia." (PMID 35040955, 2022). "The Th2 cytokines IL-4 and IL-13 bind to the IL-4/IL-13R to activate STAT-6, which plays a major role in mediating a variety of phenotypic endpoints in allergic airway inflammation, including eosinophilia, mucous cell metaplasia, and airway fibrosis." (PMID 26091108, 2015). "STAT6 has been demonstrated to regulate many pathologic features of lung inflammatory responses, including Th2 cell differentiation, airway eosinophilia, epithelial mucus production, and smooth muscle changes." (PMID 26075216, 2015). "STAT6 knockout mice fail to produce IgE, airway hyperresponsiveness and bronchoalveolar lavage eosinophilia after allergen sensitisation, suggesting a critical role for STAT6 in allergic responses." (PMID 22401596, 2012). "Some studies have shown that there was no eosinophil recruitment in STAT6-/- mice, while other groups including us contend that lung eosinophilia and inflammation are only partially dependent on STAT6." (PMID 22014099, 2011). "In this model, STAT6 and IL-4Rα expression are only partially required for inducing pulmonary inflammation and eosinophilia." (PMID 22014099, 2011). "Consistent with previous reports, Alt-induced eosinophilia was highly dependent upon STAT6." (PMID 33679760, 2021). "Importantly, STAT6–/– x IL5Tg or IL4Rα–/– x IL5Tg mice had comparable blood eosinophilia, and ILC2 expansion after IL-33 treatment was equivalent." (PMID 33974563, 2021). "Additionally, DClps treatment dramatically diminished infiltration of inflammatory cells, eosinophilia, serum IgE and STAT6 phosphorylation level, increased the number of pulmonary Tregs." (PMID 34093516, 2021). "Therefore, it is not surprising that the biological and clinical features observed, such as autoimmunity, inflammation, elevated IgE, eosinophilia, and recurrent infections, overlap with those reported in patients carrying GOF variants in STAT1, STAT5, or STAT6." (PMID 41136770, 2025). "The reduced expression of FIZZ1 and YM1 in the absence of STAT6 or IL-4Rα may be functionally linked to the reduced inflammation and eosinophilia seen in STAT6xRAG2-/- and IL-4RαxRAG2-/- mice." (PMID 22014099, 2011). "Like ILC2del mice, IL4Rα–/– x IL5Tg and STAT6-–/– x IL5Tg mice were protected from pulmonary hemorrhage after IL-33 administration and had dramatically reduced BAL eosinophilia compared with controls." (PMID 33974563, 2021). "Furthermore, while IL-4/IL-13 signaling through IL-4Rα and STAT6 is essential for AAM protein expression, lung inflammation and eosinophilia are only partially dependent on this pathway." (PMID 22014099, 2011). "Thus it appears that while IL-4/IL-13 signaling through IL-4Rα and STAT6 is essential for induction of AAM genes, lung inflammation and eosinophilia are only partially dependent on this pathway." (PMID 22014099, 2011). "We found that in the absence of STAT6 and IL-4Rα, mice developed less pulmonary inflammation, reduced perivascular and peribronchial cuffing and decreased eosinophilia than our control mice." (PMID 22014099, 2011). "In fact, STAT6 knockout mice have no response to IL-4 and IL-13, do not develop Th2 cells in response to IL-4, fail to produce IgE, airway hyperresponsiveness and bronchoalveolar lavage eosinophilia following allergen sensitisation." (PMID 22401596, 2012). "By contrast, in other systems, STAT6 is not required for tissue eosinophilia." (PMID 21423619, 2011).
viral infection (19 papers, 2013 to 2023). "First, IL-13−/− and STAT-6−/− mice were far more susceptible to WT or mutant virus infection than IL-4−/− mice." (PMID 25751266, 2015). "Interestingly, 39 genes were dramatically upregulated by transfection with exogenous STAT6, most of which encoded cellular receptors and growth factors and were mainly involved in the regulation of viral infection, metabolism, and tumor formation." (PMID 30532138, 2018). "Finally, mice deficient in IL-13 or STAT-6 were significantly more susceptible than WT animals in response to WT or mutant virus infection." (PMID 25751266, 2015). "STAT6 contributes to defence against viral infection by mediating immune signaling in the endoplasmic reticulum." (PMID 37372448, 2023). "STAT6 is required for innate and adaptive immune signaling in response to virus infection or signals from extracellular cytokines through JAK-dependent or JAK-independent pathways." (PMID 36313547, 2022). "Specifically, in the context of viral vector-based vaccination whilst IL-13/STAT6 signalling has been shown to dampen effective antiviral immunity, however in acute and primary viral infections, it has shown to improve antiviral immunity." (PMID 31974500, 2020). "We evaluated the effect of the activation of the different pathways (TLR9, STING, STAT6) due to viral infections on the cytokine and chemokine expression by primary NK cells." (PMID 32140147, 2020). "This virus-induced STAT6 activation is commonly detected in all cell types, suggesting its fundamental role in the host immune defense against viral infections." (PMID 30532138, 2018). "A recent report suggested that STING is required for Sendai virus-induced phosphorylation of STAT6 on Y641, and leads to STAT6 translocation in nucleus after virus infection." (PMID 28099521, 2017). "Emerging evidence implies that STAT6 plays an important role in both the adaptive and innate immune responses to virus infection." (PMID 28099521, 2017). "Of note, STAT-6−/− mice infected with WT virus had the lowest number of IFN-γ producing CD4 T cells but it was the only strain in which mutant virus infection increased numbers significantly by nearly 90-fold." (PMID 25751266, 2015). "Absence of vIFN-γbp during infection had minimal effects on CD4 T cell responses with the exception of STAT-6−/− mice in which mutant virus infection significantly increased IFN-γ+ CD4 T cell numbers." (PMID 25751266, 2015). "Data indicate that the amount of IL-4 available during virus infection can regulate the expression of IL-4Rα on CD8+ T cells in a STAT6 dependent manner." (PMID 23383283, 2013). "Thus, STAT6 mediates the comprehensive regulation of immune signaling in response to both the stimulation of cytokines at the plasma membrane and viral infection in the endoplasmic reticulum." (PMID 30532138, 2018). "STAT6 deficiency not only affects macrophage development, but it also impairs major histocompatibility complex (MHC) class II expression and nitric oxide production, which results in higher susceptibility to viral infection." (PMID 30532138, 2018). "In addition, recent studies have shown that primary virus infection can induce STAT6 activation in the endoplasmic reticulum independently of JAK, but it relies on a stimulator of interferon genes and TANK-binding kinase 1 for antiviral innate immunity." (PMID 30532138, 2018). "That study further defined STAT6 as a critical factor for survival during primary viral infection." (PMID 27143388, 2016). "Recently, the adaptor protein endoplasmic reticulum IFN stimulator (STING, also known as MITA/ERIS), along with MAVS and TBK1, were identified for their contribution to STAT6 activation during viral infection with Semiliki Forest virus and herpes simplex virus 1 (HSV-1)." (PMID 27143388, 2016). "Previous studies have shown that STAT6 activation is ubiquitously detected during viral infections, concluding that STAT6 may play a fundamental role in the defense mechanism against viral infections." (PMID 23651608, 2013).
viral infection (continued). "STAT6 comprises 850 amino acids, with tyrosine 641 as its phosphorylation site; however, S407 could be the critical phosphorylation point for the total activation of STAT6 in response to a viral infection." (PMID 37372319, 2023). "In addition to playing a key role in the regulation of extracellular cytokines and viral infection, STAT6 is also involved in the immune response against nematode infection and the development of allergic inflammatory disease (i.e., airway hyper responsiveness or eosinophilic inflammation)." (PMID 30532138, 2018). "Studies have shown that STAT6 and STAT3 can be differentially regulated, according to the state of viral infection/vaccination." (PMID 31974500, 2020). "We found that viral infection increased the phosphorylation of STAT3 and to a lesser extent of STAT6, molecules activated in M2 polarised macrophages." (PMID 32418990, 2020). "STAT6, a member of the signal transducer and activator of transcription (STAT) family, has been shown to play an important role in viral infection." (PMID 28099521, 2017). "Flow cytometric analysis revealed that WT virus infection increased GzB+ NK cell (CD3-DX5+) numbers in IL-4−/− and STAT-6−/− mice compared to WT mice." (PMID 25751266, 2015). "vIFN-γbp modulated the IFN-γ response only in STAT-6−/− mice but that did not assist in the recovery of this strain from mutant virus infection." (PMID 25751266, 2015). "In addition to potential applications of STAT6 inhibitors in TH2-driven diseases, they may also be useful to prevent excessive inflammatory responses in viral infection or treat autoimmune disease by increasing adenosine signaling." (PMID 35730568, 2022). "The observation that STAT6/STING contribute to type I IFN production and survival during primary virus infection suggests that STING and STAT6 may be involved in the control of IL-13 and type I IFN production and susceptibility to post-IAV infection superinfection." (PMID 27143388, 2016).
liposarcoma (18 papers, 2014 to 2026). A usually painless malignant tumor that arises from adipose tissue. "Potential diagnostic pitfalls could be STAT6 expression in, for example, the morphologic mimics deep benign fibrous histiocytoma and dedifferentiated liposarcoma, especially in retroperitoneal and abdominal localization." (PMID 25432794, 2014). "STAT6 amplification, which occurs in a subset of dedifferentiated liposarcoma, can be a potential pitfall." (PMID 38388450, 2024). "Particularly among other CD34 positive tumours, STAT6 is a useful SFT diagnostic marker due to the NAB2-STAT6 fusion in SFTs and some other soft tissue tumours, such as dedifferentiated liposarcoma express STAT6." (PMID 32566457, 2020). "Expression of STAT6 in ca. 10% of dedifferentiated liposarcomas is based on amplification of the corresponding gene located in proximity to MDM2 and CDK4." (PMID 25432794, 2014). "Well-differentiated liposarcomas should also stain negative for STAT6 and have no loss of RB expression, unlike the dedifferentiated and pleomorphic liposarcoma subtypes, respectively." (PMID 41141132, 2025). "STAT6 nuclear expression is not exclusive to SFTs and has also been reported in dedifferentiated liposarcoma, glioma-associated oncogene homolog 1 (GLI1)-amplified tumor, Kaposi sarcoma and Hodgkin as well non-Hodgkin lymphomas." (PMID 34502329, 2021). "Of note, a small subset of dedifferentiated liposarcomas (DDLPS) may show expression since the STAT6 gene may be co-amplified with its neighboring genes, MDM2 and CDK4." (PMID 33921435, 2021). "STAT6 expression has also been reported in dedifferentiated liposarcoma and GLI1-amplified tumors; hence, in cases with overlapping morphology and STAT6 immunoreactivity, additional molecular studies are needed to establish a definitive diagnosis." (PMID 34502329, 2021). "CDKN2A/B), amplifications (e.g. JUN in liposarcoma), fusion partners (e.g. PAX3/7::FOXO1 in rhabdomyosarcoma), breakpoint positions in fusions (e.g. NAB2::STAT6 in SFT) and the extent of segmental (i.e. sub-chromosomal arm) copy number changes (e.g. synovial sarcoma)." (PMID 38997407, 2024). "However, STAT6 positivity alone may not be sufficient to distinguish some cases of SFT from its histologic mimic well-differentiated/dedifferentiated liposarcoma." (PMID 33856588, 2021). "Case 4 with negative staining for CD34 and absence of a detectable gene fusion showed strong nuclear expression of STAT6 and no MDM2 amplification, so the possibility of being a dedifferentiated liposarcoma was ruled out." (PMID 25432794, 2014).